SMAD4 (SMAD family member 4)
Diseases named in the same sentence as SMAD4 in open-access papers (continued):
Sharing a sentence is not in itself a finding about the gene and the disease.
tumor (continued). "The vast majority of these mutations were also observed in the matched tissue samples, except for one SMAD4 mutation in CAS-DAC-16, which might be due to tissue heterogeneity or the higher tumor purity of the organoid model or could be an additional mutation acquired during culture." (PMID 35449156, 2022). "However, SMAD4 has also been reported to trigger EMT through the induction of EMT-associated transcriptional factors Snail, ZEB1, and ZEB2, or to function as a tumor promoter." (PMID 36088360, 2022). "Thus, the defective SMAD4 in human CRC cells may seem to be correlated with tumor-infiltrating immune cells and its chemokines and receptors." (PMID 35935996, 2022). "Hence, while SMAD4 signaling may modestly reduce PD-L1 expression in tumor cells, SMAD4 functions as an indirect inducer of PD-L1 by enhancing the recruitment of tumor-infiltrating IFNγ-producing T-lymphocytes." (PMID 35155243, 2022). "Smad4 also performs TGFβ-independent functions that include silencing the expression of TGFβ target genes in T-lymphocytes (T-cells), upregulating genes that promote natural killer (NK) cell maturation, and tumour suppression by mediating Aurora A kinase degradation." (PMID 36267157, 2022). "In short, tumor cells with low functional SMAD4 expression may be radio-sensitive." (PMID 36088360, 2022). "Interestingly, this effect was only observed for SMAD4+ PDA tumor cells-derived EVs." (PMID 34207163, 2021). "The theory, which is advocated by our findings, proclaims that Act-A may deter the advance of Smad4-positive tumours, whilst it could induce progression through non-canonical oncogenic pathways following the loss of Smad4 protein during the late stages of CRC." (PMID 34867090, 2021). "However, SMAD4 gene mutation has no connection with other clinicopathology parameters, including patient age, gender, tumor grade, MSI status and BRAF status." (PMID 34301194, 2021). "Inactivating mutation in SMAD4 does not initiate the tumour genes in PDAC but serve as secondary genetic alterations following KRAS mutation, which was consistent with our genomic finding that both KRAS and SMAD4 had higher mutation frequency in pancreatic body/tail cancers." (PMID 33452856, 2021). "Thus, our study is the first extended exploration of the tumor biological significance of SMAD4 in a large and well characterized Caucasian patient population confirming the independent prognostic significance of SMAD4 expression in GC." (PMID 34749812, 2021). "Moreover, the activin-A actions in CRC could be Smad4-dependent, whereas activin-AB may act as a Smad4-independent tumour suppressor protein." (PMID 34867090, 2021). "Since the loss of SMAD4 expression is responsible for increased glycolysis in cancer cells due to the overexpression of glucose transporters, the loss of SMAD4 in PDA cells also led to an increased expression of PGK1, enhancing glycolysis and more aggressive tumor progression." (PMID 33804240, 2021). "Interestingly, SMAD4 mutations are associated with tumor size, lymphatic invasion, and metastasis and no survival at 5 years." (PMID 33889150, 2021).
tumor (continued). "Although SMAD4 haploinsufficiency alone did not induce tumor initiation, loss of chromosome 18 could represent an evolutionary advantage in SINETs explaining the high prevalence of this aberration." (PMID 33509126, 2021). "Moreover, a significant correlation was reported between methylation status of both PTEN and SMAD4 (P = 0.0001), and this could be attributed that both are tumor suppressor genes related to TGF-β pathway." (PMID 33825073, 2021). "Indeed, while the tumor-suppressive functions of SMAD4 are well established in mediating cell cycle arrest and apoptosis, it is clear that SMAD4 is also required for tumor progression, notably by mediating TGFβ-induced expression of EMT transcription factors, such as SNAIL, SLUG, TWIST and ZEB." (PMID 34571856, 2021). "This study is also the first to report consistent decreases in Act-AB with CRC progression and the protein induced cell cycle arrest and increased the markers of apoptosis in the SW480 and HT29 cells, implying that it could act as a Smad4-independent tumour suppressor." (PMID 34867090, 2021). "Interestingly, tumours with wild-type SMAD4 express significantly more RAC1B, indicating high RAC1B expression might compensate for its lack of mutation (p = 0.0004)." (PMID 34564693, 2021). "Therefore, DUSP4 plays a biological role in tumor promotion, but Smad4 might act a suppressive effect." (PMID 32897241, 2020). "PDAC with an impaired TGF-β-SMAD4 signalling pathway per se may modulate the fibrotic response and mechanophenotype, indicating that molecular alterations in tumours not only control PDAC progression but also reprogram the metabolic phenotypes of cells in the TME." (PMID 33008426, 2020). "In addition, BRIP1 might contribute to BC bone metastasis by switching the SMAD pathway; (SMAD4 was down‐regulated by (−3.5) fold) from the known tumour suppression role to pro‐metastatic one." (PMID 32888398, 2020). "In addition, Smad4 is involved in the maintenance of tumor stem cells and inhibition of apoptosis." (PMID 32897241, 2020). "Moreover, our study revealed that the driver genes mutation of tumor cell might program the tumor microenvironment, and the expressions of Shh and Gli1 were found to be related to the status of SMAD4/DPC4." (PMID 31417657, 2019). "The unresponsiveness of advanced cancers to the tumor-restricting properties of TGFβ is a consequence of either genetic mutations of downstream cytostatic genes that, otherwise, are induced by the pathway, or mutations in components of the core signaling pathway, such as TGFBR2 and SMAD4." (PMID 31450767, 2019). "Moreover, the up‐regulation of miR‐539 or DLX1 gene silencing led to the inhibition of PCa cell proliferation, migration, invasion, EMT and tumour growth, accompanied by increased E‐cadherin expression and decreased expression of vimentin, Smad4, c‐Myc, Snail1 and SLUG." (PMID 31298493, 2019). "Moreover, NIMA-related kinases 6 (NEK6) may exert a tumor-promoting effect in liver cancer by interacting with Smad4 and antagonizing the tumor-inhibitory effect of TGF-β." (PMID 31614569, 2019). "iTreg differentiation is driven by the master transcription factor, Foxp3, which is transcriptionally activated by TGFβ effectors, pSmad3 and Smad4, we thus postulated that suppression of Treg activation through blockade of TGFβ ligands might enhance α-PD-1 tumor responses." (PMID 30832732, 2019). "In addition, NDRG1 might promote tumour development via the EMT pathway by modulating SMAD4/slug expression." (PMID 30914736, 2019).
tumor (continued). "This could be due to the high heterogeneity in the applied detection methods (different antibodies and IHC methods) but could also be due to the differences in scoring algorithms and corresponding cut-offs to categorize a tumor as “SMAD4 lost” or “SMAD4 expressed”." (PMID 28534865, 2017). "Interestingly, the tumor-promoting effects shown for BMP4 stemmed from mutations in BMP4 or Smads while the tumor-promoting effects of BMP7 did not depended on Smad4." (PMID 28009989, 2017). "After adjusting for sex and age, RUNX3-/SMAD4+ status remained a significant independent predictive factor for favorable overall [p = 0.025, HR 1.842 (95% CI 1.079–3.143)] and progression-free survival [p = 0.020, HR 1.850 (95% CI 1.100–3.113)] on multivariate analysis, in addition to tumor size." (PMID 29100342, 2017). "Therefore, miR-224 promotes CRC tumor growth and metastasisviatargeting SMAD4." (PMID 28392501, 2017). "Therefore, SMAD4 functions as a tumor-suppressor through growth arrest during tumorgenesis." (PMID 28053288, 2017). "In the non-responding tumor, enrichment of the pathways 'loss of function of SMAD4 in cancer' and 'SMAD4 MH2 domain mutants in cancer' indicates that the non-responder tumor shows impaired TGFB1-related transcription initiation, which corresponds to the observed (non-responder) phenotype." (PMID 28594404, 2017). "These signalling pathways are amenable to morphologic study of tumour specimens by β-catenin or SMAD4 immunohistochemistry, respectively: as downstream-effectors in the signalling cascades, when activated, these proteins can be found in the nuclei of the tumour cells." (PMID 29040282, 2017). "SMAD4 alterations may explain the decreased tumor suppressive effect of TGF-β signaling in HNSCC." (PMID 26933913, 2016). "These mutations might prevent the normal function of SMAD4, and therefore, tumor growth is not suppressed." (PMID 27528036, 2016). "From a mechanistic viewpoint, we suggest that SMAD4 HD, which correlates with tumor progression, creates a favorable ground for the activation of pro-survival pathways when multiple inflammatory stimuli, which are likely to occur in the tumor microenvironment, target cancer cells." (PMID 27655713, 2016). "These functions of Smad4 might contribute to its critical role in preventing tumor development." (PMID 26583325, 2015). "Lack of SMAD4 expression in the tumor has been associated with more aggressive disease." (PMID 24465802, 2014). "This suggests that tumours with intact Smad4 may benefit from an increased radiotherapy dose." (PMID 24962658, 2014). "Accordingly, in this study, we examined the expression of TGF-β1, Smad2, phospho-Smad2 (p-Smad2), Smad3, phospho-Smad3 (p-Smad3), Smad4, and Smad7 in normal anterior pituitaries, invasive NFPAs, and noninvasive NFPAs and evaluated whether they were correlated with tumor development and invasion." (PMID 24636138, 2014). "In addition, the inactivation of the Smad4 gene within an evolving neoplasm may indirectly influence the extracellular matrix to promote neoplastic growth and affect the prognosis." (PMID 25333693, 2014). "Interestingly, we found that knockdown of either TβRII or Smad4 attenuated TGF-β-induced nuclear accumulation of p-Smad3L suggesting that the tumor-promoting activity of autocrine TGF-β is likely mediated in part by its stimulation of linker region phosphorylation of Smad3." (PMID 23704908, 2013). "Smad4 was proposed to be a tumor-suppressor gene that may function to disrupt TGF-β signaling." (PMID 23717813, 2013).
tumor (continued). "However, genetic studies in mice indicate that loss of Smad4 is not sufficient to cause the development of PDAC but contributes to tumor progression in the presence of additional oncogenic alterations." (PMID 24340014, 2013). "Using these models, we have shown that Smad4 functions as a potent tumor suppressor and its loss causes spontaneous SCCs development; Smad2 functions as a tumor suppressor and its loss promotes SCC formation initiated by other genetic insults but is insufficient to initiate tumor formation." (PMID 22204491, 2011). "Smad4 haploinsufficiency is sufficient to significantly inhibit both TGF-β and BMP signal transduction and results in the differential expression of a broad subset of target genes likely to underlie tumor formation both from the mesenchymal and epithelial compartments." (PMID 19014666, 2008). "As far as the tumor-associated stroma is concerned, different mesenchymal cell types, for example stromal fibroblasts and infiltrating lymphocytes, showed in almost all cases SMAD4 nuclear reactivity amidst a variable number of negative cells." (PMID 19014666, 2008). "Rather, tumour cell-ECM interactions may be more relevant for Smad4-mediated tumour suppression." (PMID 17997817, 2007). "Therefore Smad4 expression of tumor tissues and the surrounding normal tissues was compared." (PMID 16438724, 2006). "Thus, one could have expected that inactivation of Smad4 might result in a TGFβ resistance that would favour tumour expansion." (PMID 12569386, 2003). "Intriguingly, SMAD4 palmitoylation sensitizes PDAC cells to radiotherapy both in vitro and in vivo, revealing a dual role between tumor progression and treatment responses." (PMID 41885390, 2026). "SMAD4, a pivotal mediator of TGF-β signaling pathway, is recognized as a tumor suppressor in various cancers, including CCA." (PMID 39143229, 2025). "By interacting directly with NSCLC cell Smad family members (Smad2, Smad3, and Smad4), MELK inhibits EMT and increases tumor cell motility, invasion, and metastasis." (PMID 40925573, 2025). "Consistent with previous findings, our data confirm its tumor-suppressive role in OSCC, as SMAD4 silencing enhances proliferation, migration, and invasion while reducing apoptosis, whereas its overexpression gives opposite effects." (PMID 40338154, 2025). "Smad4, a central mediator of the TGF-β pathway, functions as a tumor suppressor in OSCC by inhibiting proliferation, inducing apoptosis, and preventing metastasis." (PMID 40507242, 2025). "Meanwhile, SMAD4, which is a central mediator of TGF-β signaling, remains functionally undruggable, as its tumor suppressor function is typically lost through biallelic inactivation rather than amenable to pharmacologic inhibition." (PMID 41009646, 2025). "Notably, the nonsense mutation of SMAD4 in PT_3 was not directly retained in PDO_3, which may be due to the intra-tumor cell diversity that occurred during the tumor progression." (PMID 40001264, 2025).
tumor (continued). "SMAD4 is a key mediator of the TGF-β signaling pathway, which is traditionally known for its tumor-suppressive functions, including the induction of cell cycle arrest and apoptosis in normal cells." (PMID 40224178, 2025). "Specifically, the upregulation of SMAD1, SMAD3, SMAD4, BMP2, MAPK1, and SKIL—driven by promoter hypomethylation and reduced expression of tumor-suppressive microRNAs—leads to enhanced activation of both canonical and non-canonical branches of TGF-β signaling." (PMID 40869118, 2025). "SMAD4-dependent enhancement of bone morphogenetic protein (BMP) signaling, inducing cell differentiation and suppressing tumor growth in specific molecular subtypes (SMAD4-intact tumors)." (PMID 41170235, 2025). "Mechanistically, this process involves suppression of the TGF-β/Smad4 tumor suppressor pathway, establishing an ARID1A-TGF-β-Smad4 axis as critical in preventing biliary carcinogenesis." (PMID 41008893, 2025). "SMAD4, a critical transcription factor in the TGF‐β pathway, typically transduces tumor‐suppressive signals." (PMID 40182139, 2025). "The combination of protein- and gene-expression analyses, along with functional assays, underscores the importance of Smad4 in regulating EMT and tumor aggressiveness." (PMID 40507242, 2025). "This study aims to evaluate the expression patterns of Smad4 and EMT markers in human OSCC tissues and cell models, elucidating their roles in tumor progression and metastasis." (PMID 40507242, 2025). "SMAD4, a highly conserved transcription factor and a central signaling transducer of the TGF-β pathway, is a well-known tumor-suppressor gene in several cancers and it functions by regulating tumorigenesis and differentiation." (PMID 40338154, 2025). "Smad4 is a key transcription factor in the TGF-β signaling pathway, which influences tumor growth and EMT." (PMID 40507242, 2025). "Our findings position AMDHD1 as a pivotal prognostic marker and tumor suppressor, offering a novel therapeutic avenue through the combined targeting of AMDHD1 and SMAD4 in CCA." (PMID 39143229, 2025). "Smad molecules, such as R-Smads (Smad2, Smad3) and Co-Smad (Smad4), are central mediators of the canonical TGF-β pathway and play critical roles in effectuating TGF-β-mediated EMT, leading to tumor progression." (PMID 39518973, 2024). "Ablation of KDM3A, KLF5, SMAD4, or EGFR elevates the population of tumor-infiltrating T cells and dendritic cells and decreases myeloid cell infiltration." (PMID 39519018, 2024). "Overexpression of SMAD3, SMAD4, and SMAD5 suggests excessive activation of the TGFβ pathway, potentially promoting tumor growth and development." (PMID 39337574, 2024). "Mechanistically, W. coagulans MZY531 postbiotics inhibit tumor growth through the modulation of the Bax/Bcl-2/caspase-3 and JAK2/STAT3 apoptosis pathways and PI3K/AKT/mTOR and TGF-β/SMAD4 cell autophagy pathways." (PMID 39459634, 2024).